LINC00326 (long independently transcribed non-coding RNA 326)
Synonyms: NCRNA00326
Gene: Long non-coding RNA gene on chromosome 6 (132,908,105 to 133,107,410, forward strand). Ensembl gene ENSG00000231023.
Diseases named in the same sentence as LINC00326 in open-access papers:
LINC00326 is named in the same sentence as 6 diseases in open-access papers, as found by Europe PMC text mining. Sharing a sentence is not in itself a finding about the gene and the disease. The quoted sentences say what the papers report.
gastric cancer (1 paper, 2023). A primary or metastatic malignant neoplasm involving the stomach. "These analyses showed 15 genes were implicated in the prognosis of gastric cancer, including AC011374.1, AC018781.1, ADAMTS9-AS1, AL139002.1, AL391152.1, HOTTIP, FLRT1, NKX2-1-AS1, ADAMTS9-AS2, LINC00326, VCAN-AS1, SERPINE1, POU6F2-AS2, IGF2-AS, and miR-145." (PMID 37696973, 2023). "A survival study identified 15 genes associated with gastric cancer prognosis, including VCAN-AS1, SERPINE1, AL139002.1, LINC00326, AC018781.1, C15orf54, hsa-miR-145." (PMID 37696973, 2023).
lipid metabolism disorders (1 paper, 2022). "Since these assays confirmed that alteration of CCT3 and LINC00326 gene expression levels modulate regulation of lipid metabolism, we inspected publicly available data from patient liver biopsies with lipid metabolism disorders (GSE126848 and TCGA)." (PMID 35022268, 2022).
liver cancer (1 paper, 2022). An epithelial or non-epithelial malignant neoplasm that arises from the liver. "In contrast, LINC00326 abundance was low in tumour tissues but increased after the CCT3-KD in liver cancer cell lines." (PMID 35022268, 2022).
testicular cancer (1 paper, 2023). A primary or metastatic malignant neoplasm that affects the testis. "LINC00326 gene expression is almost completely diminished in testicular cancers and gradually decreases with increased testicular cancer severity." (PMID 36747258, 2023).
tumor (3 papers, 2022 to 2025). "The expression of LINC00326 in NSCLC tumor tissues and cell lines was investigated using multiple assays." (PMID 36747258, 2023). "Knockdown of LINC00326 stimulated NSCLC cell proliferation and suppressed apoptosis in vitro, as well as enhancing xenograft tumor growth." (PMID 36747258, 2023). "CCT3-KD and LINC00326-OE resulted in a significant suppression in tumour growth in comparison to the respective controls confirming that low CCT3 and high LINC00326 gene expression reduced tumour burden." (PMID 35022268, 2022).
LINC00326 also shares sentences with these, for which no sentence is quoted: cancer (1 paper).